ROS1 (ROS proto-oncogene 1, receptor tyrosine kinase)
Diseases named in the same sentence as ROS1 in open-access papers (continued):
Sharing a sentence is not in itself a finding about the gene and the disease.
cancer (continued). "The chromosomal rearrangement in a variety of cancers activates the ROS1 proto-oncogene, causing cellular transformation." (PMID 30791612, 2019). "ROS1 G2032R is also analogous to the G595R mutation in NTRK1 identified in entrectinib-resistant NTRK1-rearranged cancer." (PMID 31399568, 2019). "ROS1 is a proto-oncogene located on the long arm of chromosome 6 and encodes a receptor tyrosine kinase involved in the regulation of cancer cell growth and differentiation." (PMID 30719217, 2019). "Epidermal growth factor receptor (EGFR), anaplastic lymphoma kinase (ALK), v-raf murine sarcoma viral oncogene homolog B1 (BRAF), and c-ros oncogene 1 (ROS1) mutations are now used to guide specific anti-cancer therapies to improve patient outcomes." (PMID 30065223, 2018). "This lack of participation may be attributed to the rarity of ALK or ROS1 mutations in these cancers." (PMID 38399413, 2024). "However, it is important to note that the overall frequency of ROS1 activating mutations in the cancer genome is low, at ≤ 0.5%." (PMID 37587872, 2023). "Resistance to Crizotinib in cancers may develop due to various mechanism, including secondary mutations in the structural region of the ROS1 kinase or amplification of the ROS1 gene." (PMID 37375228, 2023). "Additionally, some ROS1-positive cancers demonstrate a second driver mutation, mainly KRAS and EGFR, after initial treatment with a TKI." (PMID 33172113, 2020). "Entrectinib (Ignyta) was FDA‐approved only for molecularly defined subsets of NSCLC, and may also be effective in ROS‐1 mutated cancers." (PMID 31799812, 2020). "At the time we submitted this paper, no drug had proven to overcome G2032R-mutated ROS1 fusion in clinic, but while our paper reviewed, it was reported TPX-0005 (Repotrectinib) showed activity against ROS1-G2032R mutation positive cancer patient in phase 1/2 clinical trial." (PMID 31399568, 2019). "ROS1 somatic mutations and focal amplification were reported at a very low frequency in cancer, and the significance of these genetic alterations is largely unknown." (PMID 26802023, 2016). "Collectively, these data indicated that FAK activation was related to ROS1 inhibitor (crizotinib)-resistance in CDH1-deficient cancer cells, and that FAK inhibition could thus overcome this drug resistance, ultimately leading to synergistic therapeutic effects in these cancers." (PMID 37324948, 2023). "The fact that significant parts of ROS1 localized to mitochondria and cancer metastasis was linked to dysregulated mitochondrial morphogenesis, we next investigated whether mitochondrial ROS1 could enhance OSCC invasiveness by affecting mitochondrial morphogenesis." (PMID 33019722, 2020). "In addition, genomic rearrangements in the ROS1 gene have been implicated in cancer progression." (PMID 33019722, 2020). "ROS1-directed tyrosine kinase inhibitors (TKIs) have demonstrated therapeutic efficacy against these cancers." (PMID 41179684, 2025). "This broad distribution pattern underscores the necessity of screening for NTRK, ALK, and ROS1 fusions in cross‐cancer clinical practice, particularly for rare or refractory malignancies with limited standard treatment options." (PMID 41275415, 2025). "Gene fusions such as TPM3—NTRK1, TPM3—ALK, and TPM3—ROS1 have been identified as oncogenic drivers in various cancers." (PMID 41275415, 2025). "A receptor tyrosine kinase is encoded by the proto-oncogene ROS1, and somatic chromosomal fusions involving ROS1 result in chimeric oncoproteins that fuel various cancers in both adults and children." (PMID 40371229, 2025).
cancer (continued). "Similar to HER2 or ALK/ROS1 testing in other cancers, this approach holds clinical promise for OSCC." (PMID 41463200, 2025). "ROS1 tyrosine kinase inhibitors are one of the primary immunotherapies for ROS1 fusion-positive cancers." (PMID 39802058, 2025). "We investigated the ROS1 and RET fusions concerning mutation rates in the CRC (MSK, JNC 2021) study from the cBioPortal for cancer genomics database." (PMID 40572720, 2025). "In conclusion, this study is a significant step forward in the pursuit of effective therapies for ROS1-driven cancers." (PMID 39136033, 2024). "As ALK or ROS1 fusion proteins are mainly expressed in cancer cells, we mainly focused on MET kinase." (PMID 37733896, 2024). "In conclusion, the high‐frequency ROS1 fusion partners differ among cancer types and are related to the intrinsic levels of fusion gene activation and fusion sites." (PMID 38629293, 2024). "The study demonstrates the effectiveness of computational approaches in speeding up drug repurposing efforts thereby facilitating the identification of potential therapeutic alternatives for ROS1-driven cancers." (PMID 39136033, 2024). "Despite being observed in only 1% to 2% of NSCLC patients, ROS1 plays a significant role in cancer through fusion proteins resulting from ROS1 rearrangements." (PMID 38791529, 2024). "Crizotinib was the first-in-class inhibitor to gain FDA approval for ROS1-driven cancers, that show remarkable clinical efficacy." (PMID 39136033, 2024). "The therapeutic landscape has been enriched by TKIs treating cancers with mutations in kinases like JAK2, FLT3, ALK, MET, NTRK, RET, and ROS1." (PMID 39199633, 2024). "ROS1 has become an important focus in cancer therapy, with targeted inhibitors showing effectiveness against ROS1-driven cancers." (PMID 39138146, 2024). "This retrospective real-world study aimed to evaluate first-line treatment with crizotinib, a tyrosine kinase inhibitor (TKI) standard of care vs. new generation ROS1 anti-cancer agents." (PMID 39195309, 2024). "Targeted therapy is a specialized cancer treatment that uses drugs to target specific mutant proteins, such as EGFR, ALK, and ROS1, which drive the growth of cancer cells." (PMID 38254898, 2024). "A recent study has demonstrated the potential of FAK inhibitors in disrupting the FAK-YAP-TRX signaling pathway, augmenting the effectiveness of ROS1 inhibitors in cancers." (PMID 38273343, 2024). "ROS1 gene fusions have been discovered in a diverse array of cancers, including non-small cell lung cancer (NSCLC), glioblastoma, cholangiocarcinoma, and others." (PMID 39136033, 2024). "Various fusion partners of ROS1 kinase fusions have been identified in different cancers, with CD74 being the most prevalent." (PMID 38273343, 2024). "This study presents a comprehensive approach to addressing the therapeutic challenges posed by ROS1-driven cancers through drug repurposing." (PMID 39136033, 2024). "ROS1-dependent cancers are a specific group of tumors that rely on the abnormal activity of the ROS1 fusion protein for their growth and survival." (PMID 38655260, 2024). "Crizotinib, which is approved for the treatment of ALK- and ROS1-driven carcinomas, was historically developed as a MET inhibitor and, expectedly, demonstrated clinical activity towards MET-mutated carcinomas." (PMID 38966170, 2024). "The FAK inhibitor suppresses the aberrant FAK-YAP-TRX signaling, reinforcing ROS1 inhibitor's cytotoxicity towards cancer cells." (PMID 37324948, 2023). "Both of these cancers feature CDH1 gene deficiency, and synthetic lethality between ROS1 and CDH1 has already been established, providing a potential clinical treatment strategy for patients with these types of cancer." (PMID 37324948, 2023). "Currently, the involvement of ROS1 in cancer focuses on oncogenic ROS1 fusion proteins generated by chromosomal rearrangements." (PMID 37587872, 2023).
cancer (continued). "Based on the phase I/II clinical studies, Crizotinib has shown significant therapeutic potential against ROS1-fusion driven cancers." (PMID 37375228, 2023). "ROS1 fusion proteins are established oncogenic drivers in a diverse set of cancers, particularly in lung adenocarcinomas." (PMID 37587872, 2023). "An integrated analysis of three-phase 1–2 trials indicated that Entrectinib shows promising results in the treatment of ROS1 fusion-containing cancers and has been found to be 40 times more potent than Crizotinib." (PMID 37375228, 2023). "In an expression study of human cancer cell lines, ROS1 was found highly expressed in many glioblastoma cell lines but was not seen in normal healthy brain tissue." (PMID 37958963, 2023). "Here, we demonstrate that upregulation of the FAK activity accompanies the emergence of resistance to ROS1 inhibitor therapy in gastric and breast CDH1-deficient cancers." (PMID 37324948, 2023). "Point mutations in the ROS1 kinase domain that render ROS1 fusion-positive cancers resistant to ROS1 TKIs have been identified through studies in both preclinical and clinical settings." (PMID 36499382, 2022). "We investigated clinically relevant RTK fusion genes, namely ABL1, ALK, ERBB2, FGFR1-4, NTRK1-3, RET, and ROS1, because they are among the most frequent druggable cancer molecular biomarkers." (PMID 36009413, 2022). "The ROS1 fusion proteins resulting from chromosomal rearrangements of the ROS1 gene are targetable oncogenic drivers in diverse cancers." (PMID 35865478, 2022). "ROS-1 rearranged in NSCLC, like other oncogene-driven cancers, will eventually develop resistance, highlighting the need for novel ROS-1 inhibitors." (PMID 35372000, 2022). "The latest NSCLC guideline 2021 V2 edition issued by the national comprehensive cancer network (NCCN) indicated that genes associated with targeted therapy of NSCLC include EGFR, KRAS, ALK, ROS1, MET, BRAF, RET, and NTRK." (PMID 35227278, 2022). "In this study, we used an AI-based solution to detect ALK and ROS1 fusions in NSCLC cancer patients." (PMID 36057739, 2022). "The present study demonstrates that crizotinib attenuates cancer metastasis by ALK/MET/RON/ROS1-independent inhibition of TGFβ signaling in NSCLC cells." (PMID 35999455, 2022). "The ROS1 is a tyrosine kinase whose function is not fully understood, but its role in the development of resistance in some cancers made it a valuable target for management of some cancers." (PMID 35011562, 2022). "Searching for ROS1 shows that 27.3% of cases in the TCGA Pan-Cancer Atlas 2018 cohort had a heterozygous deletion." (PMID 35251754, 2022). "TCGA data show that the ROS1 protein is found in 475 missense variants (40 of which have been identified by SIFT and PolyPhen as deleterious) in 384 patients across 29 cancer types; the frequencies of these variants are below 1%." (PMID 35215249, 2022). "ROS1 is a proto-oncogene located on the long arm of chromosome 6, which encodes a receptor tyrosine kinase (RTK) and is involved in regulating of cancer cell growth and differentiation." (PMID 34396843, 2021). "For instance, cancers harboring ROS1 fusions often respond poorly to standard chemotherapy but are exquisitely sensitive to small-molecule kinase inhibitors." (PMID 34585724, 2021). "Repotrectinib shows high activity against ROS1/TRK/ALK fusion-positive cancers in preclinical studies." (PMID 34834176, 2021). "In these regards, broader investigation probing into the function of ROS1 alterations, other than rearrangement, is warranted to devise new therapeutic strategies for cancers." (PMID 34221982, 2021). "ROS1+ cancers account for around 1–3% of a dozen cancers, including non‐small‐cell lung cancer (NSCLC)." (PMID 34515408, 2021). "For instance, the use of small-molecule kinase inhibitors substantially improved treatment-response rates in patients with ALK receptor tyrosine kinase [ALK-], RET- and ROS1-rearranged cancers." (PMID 34585724, 2021).
cancer (continued). "ROS1 gene rearrangements have been reported in diverse cancer types including non‐small‐cell lung cancer (NSCLC), and with a notably higher prevalence in lung adenocarcinoma." (PMID 32871626, 2020). "We previously reported that epigenetically upregulated ROS1 expression increased cancer invasiveness and led to OSCC metastasis." (PMID 33019722, 2020). "Alterations in certain other genes, namely EGFR, HER2 and ROS1, were instead only found in patients with cancer." (PMID 32441866, 2020). "Gatekeeper or solvent front mutations frequently pose a liability for targeted kinase inhibitors, for example, ALK (ALKG1202R) and ROS1 (ROS1G2032R) recurrently arise in cancer patients treated with crizotinib, a type I ROS1/ALK/MET targeted TKI25,35,36." (PMID 33328556, 2020). "We detected ROS1 overexpression at both mRNA and protein levels in the primary lung lesions during all the stages of cancer progression and in the extrathoracic metastases developed in several organs of K-RasG12D mice." (PMID 32268572, 2020). "ROS1-positive cancers show overlapping clinical features with ALK-rearranged NSCLC, although genetic rearrangements in ROS1, EGFR and ALK tend to be mutually exclusive." (PMID 33172113, 2020). "When existing separately, activating EGFR mutations are well defined predictive effects of EGFR-TKIs in NSCLC cancer patients, and while coexisting with KRAS mutations and ALK or ROS1 gene rearrangements, the EGFR-TKIs are predicted to be resistant." (PMID 32770988, 2020). "Despite the encouraging results with entrectinib, radiation therapy is the preferred technique to treat brain metastasis; ROS1-rearranged cancers have shown significant sensitivity to this approach." (PMID 33172113, 2020). "DS-6051b inhibited the growth of the CD74-ROS1 overexpressed Ba/F3 cells and the ROS1 fusion-positive HCC78 cancer cell line with a lower IC50 than crizotinib." (PMID 31399568, 2019). "Most of the molecular-targeted drugs used in the treatment of NSCLC inhibit specific targets that induce cancer evolution [so-called “oncogenic drivers (i.e., EGFR mutation, ALK translocation, ROS1 translocation, and BRAF mutation)”]." (PMID 31049758, 2019). "This is followed by a review of the role played by ROS1 rearrangements in cancer, as well as the evidence supporting the use of targeted therapies against the resulting fusion protein." (PMID 30719217, 2019). "DS-6051b induces dramatic growth inhibition of both wild type and G2032R mutant ROS1–rearranged cancers or NTRK-rearranged cancers in vitro and in vivo." (PMID 31399568, 2019). "The identification of a ROS1- GOPC fusion has significant clinical implications due to the established anti-cancer activity of TKIs in tumors that carry ROS1 rearrangements." (PMID 30719217, 2019). "Here we characterize a new selective ROS1/NTRK inhibitor, DS-6051b, in preclinical models of ROS1- or NTRK-rearranged cancers." (PMID 31399568, 2019). "Subsequent studies demonstrated that a similar kinase, ROS1, is also recurrently rearranged in LC, and ROS1-driven tumors represent another category of crizotinib-responsive cancers." (PMID 30211169, 2018). "Activation of EGFR, which enables cancer cells to bypass crizotinib-mediated inhibition of ROS1 signalling, has been described as a mechanism of resistance to crizotinib in ROS1-rearranged NSCLC." (PMID 30029601, 2018). "Gene rearrangement of the 3′ UTR region of ROS1 with many different genes occurs in several cancer cells and activates downstream effectors to promote tumorigenesis, including ERK, AKT, and STS3." (PMID 30473665, 2018). "In the present study, we established two lines of ROS1-TKI–addicted cancer cells by ENU mutagenesis screening, namely CD74-ROS1–positive Ba/F3 cells harbouring either F2004V or F2075C mutations." (PMID 28717217, 2017). "We also summarize the ongoing and completed clinical trials validating ALK and ROS1 as targets for cancer treatment." (PMID 26802023, 2016).
cancer (continued). "ROS1 fusions were detected as a potential oncodriver in a NSCLC cancer patient (with the CD74-ROS1 rearrangement)." (PMID 27528792, 2016). "Aberrant expression of ROS1, ALK or c-MET (RAM) is implicated in carcinogenesis and cancer drug resistance." (PMID 27136744, 2016). "Given the recent success of molecularly targeted therapies in treating cancers driven by oncogenic kinases, there is acute clinical momentum to identify inhibitors that selectively target ROS1 fusions." (PMID 25978031, 2015). "Immunohistochemical analyses using an anti-ROS1 rabbit monoclonal antibody (D4D6) have recently shown to accurately identify ROS1-rearranged cancers showing 100% (8/8) sensitivity and 100% (138/138) specificity when compared with break-apart FISH." (PMID 26366867, 2015). "Increased expression of ROS1 in various cancers has prompted the development of selective inhibitors." (PMID 24386191, 2013). "Collectively, these studies underline the importance of ROS1 and TRK-A in promoting cancer and inflammatory diseases and further demonstrate the potential therapeutic utility of limited kinase cross-reactivity." (PMID 24386191, 2013). "There are a few studies showing ROS1 or TRK-A overexpression in cancers, but individual or combined expression of ROS1 and TRK-A in a broad range of cancers was thus far poorly characterized." (PMID 24386191, 2013). "For instance, GAK and ROS1 had a relatively low Z-score, but still these were considered to have an important role in the cancer survival and/or proliferation process when combined with the other selected kinases." (PMID 24068907, 2013). "We discovered novel gene rearrangements in diverse human cancer types, including fusions of ROS1, SLC1A2, RAF1, EWSR1, CDK6, and CLTC." (PMID 23637631, 2013). "Crizotinib is an anti‐cancer drug that inhibits both ROS1 and ALK (anaplastic lymphoma kinase)." (PMID 39568175, 2025). "Consequently, while ALK and ROS1 inhibitors have shown promise in other cancers, their applicability in iCCA remains limited due to the rarity of these genetic alterations." (PMID 41465387, 2025). "Genomic alterations in anaplastic lymphoma kinase (ALK) and c-ros oncogene 1 (ROS1) have been previously identified to be associated with a very high risk of VTE, whereas lower rates were reported for EGFR-mutated and ALK/ROS1/EGFR-wildtype cancers." (PMID 39858040, 2025). "Unlike ROS1 kinase domain mutations that drive tyrosine kinase inhibitor (TKI) resistance in fusion-positive cancers, somatic ROS1-Mut in both the MSKCC and TCGA cohorts were distributed broadly across the protein (e.g., extracellular, transmembrane, cytoplasmic, and kinase domains)." (PMID 40873541, 2025). "In our study, we analyzed the effects of lorlatinib, a different anti‐cancer drug targeting ROS1 and ALK, to determine whether ROS1 pathway can be an effective target for male contraceptives." (PMID 39568175, 2025). "Out of this series of 270 patients with a definitive diagnosis of cancer, molecular testing was carried out on 142 patients, looking for epidermal growth factor receptor (EGFR), anaplastic lymphoma kinase (ALK), c-ros oncogene 1 (ROS1) and PD-L1 mutations." (PMID 39941279, 2025). "Moreover, numerous oncogenic drivers (ALK, BRAF, EGFR, MET, NRG1, NTRK1/2/3, RET, and ROS1) involved in sole reciprocal fusions were found in those cancers." (PMID 39254060, 2024). "An array of studies revealed the significance of ROS1 in cancer therapeutics." (PMID 39136033, 2024). "In addition, CDX2-suppressed cancers had a higher prevalence of mutations in several receptor tyrosine kinase genes, including EGFR, ERBB3, ERBB4, RET, and ROS1." (PMID 39452477, 2024).